LINC01198 (long independently transcribed non-coding RNA 1198)
Gene: Long non-coding RNA gene on chromosome 13 (46,455,130 to 46,534,656, reverse strand). Ensembl gene ENSG00000231817.
Diseases named in the same sentence as LINC01198 in open-access papers:
LINC01198 is named in the same sentence as 5 diseases in open-access papers, as found by Europe PMC text mining. Sharing a sentence is not in itself a finding about the gene and the disease. The quoted sentences say what the papers report.
glioma (4 papers, 2019 to 2021). A benign or malignant brain and spinal cord tumor that arises from glial cells (astrocytes, oligodendrocytes, ependymal cells). "In addition, biological roles of LINC01198 implicated in the proliferation and invasion of glioma cells were defined here, exhibiting that LINC01198 can profoundly enhance the proliferation and invasion of glioma cells." (PMID 32246817, 2020). "Collectively, the data we showed here indicate that LINC01198 plays a pivotal role in the proliferation of glioma." (PMID 32246817, 2020). "Many lncRNAs had been elaborately discussed in this chemoresistance in glioma, such as LINC01198, SNHG15, and MALAT1." (PMID 33817241, 2020). "Taken together, our findings suggest a role of LINC01198 in promoting glioma progression and provide a potential therapeutic target for glioma." (PMID 31469661, 2019). "Data derived from the GSE16011, CGGA and REMBRANDT datasets verified LINC01198 overexpression in glioma." (PMID 31469661, 2019). "CCK-8 assay result showed that knockdown of LINC01198 impaired glioma cell proliferation, whereas LINC01198 overexpression promoted cell proliferation in vitro." (PMID 31469661, 2019). "Overexpression of LINC01198 by enhancing the NEDD4-1-dependent repression of PTEN could promote glioma cell proliferation and resistance to TMZ." (PMID 34178658, 2021). "To get insight into the observation we made that LINC01198 was dramatically up-regulated in glioma compared with matched normal controls; attempt has been made naturally to subject the promoter sequence of LINC01198 to bioinformatically analyze with the aid of JASPAR software on line." (PMID 32246817, 2020). "Additionally, reduced LINC01198 expression neither inhibited cell proliferation nor increased glioma cell resistance to temozolomide in NEDD4-1 knockout glioma cells." (PMID 31469661, 2019).
melanoma (2 papers, 2022 to 2025). A malignant, usually aggressive tumor composed of atypical, neoplastic melanocytes. "Previous report showed LINC01198 interacts with and activates the NF-κB component p65 to trigger type I and type II interferon responses in melanoma." (PMID 41145465, 2025). "Mechanistically, LINC01198 interacts and activates NF-κB component p65 to trigger the type I and type II interferon responses in melanoma and breast cancer cells." (PMID 36475797, 2022). "According to TCGA database, the expression levels of LINC01198 in most cancers were extremely low but significantly-higher expressed in melanoma compared with normal tissues, suggesting higher expression of LINC01198 may endow special function in melanoma." (PMID 41145465, 2025). "Mechanistically, LINC01198 associates with TAOK1/2 to attenuate their phosphorylation and following enzymatic cascade, which potentiates nuclear transportation of YAP/TAZ to transcriptionally promote IL1B expression and enhance the viability of melanoma cells treated with vemurafenib." (PMID 41145465, 2025). "Mechanistically, LINC01198 directly associates with TAOK1/2 to inhibit TAOK1/2 phosphorylation and thereby elicits Hippo signaling through TAOK/LATS axis, which redistributes YAP/TAZ into nucleus and promotes the expression and secretion of IL-1β to support vemurafenib resistance in melanoma." (PMID 41145465, 2025). "To explore how LINC01198 influences IL1B expression, we first determined the subcellular localization of LINC01198 in vemurafenib-resistant melanoma cells by fluorescent in situ hybridization (FISH) and nuclear-cytoplasmic fractionation." (PMID 41145465, 2025).
tumor (3 papers, 2020 to 2025). "Knockout of LINC01198 significantly delayed tumor growth and resulted in smaller tumor size compared with control A375R cell-derived xenografts." (PMID 41145465, 2025). "LINC01198 regulates tumor inflammation signaling pathway through activation and interaction with NF-κB component p65." (PMID 36475797, 2022). "Meanwhile, the other 13 lncRNAs (AC008781.2, HULC, AC100839.1, CRAT37, LINC01198, LINC01482, SMAD1‐AS2, TH2LCRR, DISC1‐IT1, ABCC5‐AS1, NFIA‐AS1, AC007431.1, AC012494.1) were up‐regulated and hypomethylated in CC tumor group which confirmed our previous MethylRad sequencing results." (PMID 32869528, 2020).
LINC01198 also shares sentences with these, for which no sentence is quoted: breast carcinoma (1 paper); cancer (1).